PRRG4 (proline rich and Gla domain 4)
Description:
May control axon guidance across the CNS. Prevents the delivery of ROBO1 at the cell surface and down-regulates its expression.
Synonyms: PRGP4; TMG4
Tractability: Antibody: UniProt places it where antibodies can reach, with high confidence; its Gene Ontology location is reachable by antibodies, with high confidence; UniProt predicts a signal peptide or a membrane-spanning region. PROTAC: ubiquitination databases record sites on it.
Gene: Protein-coding gene on chromosome 11 (32,829,675 to 32,858,120, forward strand). Ensembl gene ENSG00000135378.
Subcellular location: Endoplasmic reticulum-Golgi intermediate compartment membrane; Cell membrane
Subcellular location (Human Protein Atlas): Golgi apparatus
Gene Ontology:
Molecular function: protein binding; WW domain binding; serine-type endopeptidase activity; calcium ion binding
Biological process: blood coagulation; proteolysis
Cellular component: endoplasmic reticulum-Golgi intermediate compartment membrane; plasma membrane; membrane; extracellular region
Genetic constraint (gnomAD): Loss-of-function variants: 5 observed, 7.38 expected, observed/expected ratio (o/e) 0.68, 90% interval 0.35 to 1.41. That is too few expected variants to judge how well the gene tolerates losing a copy. Missense variants: 120 observed, 149.99 expected, observed/expected ratio (o/e) 0.8, 90% interval 0.69 to 0.93. Synonymous variants: 58 observed, 57.54 expected, observed/expected ratio (o/e) 1.01, 90% interval 0.81 to 1.25.
Homologues: Orthologues: chimpanzee PRRG4 (99% identical), macaque PRRG4 (96% identical), dog PRRG4 (85% identical), pig PRRG4 (84% identical), rabbit PRRG4 (82% identical), rat Prrg4 (76% identical), mouse Prrg4 (75% identical), guinea pig PRRG4 (69% identical), zebrafish prrg4 (43% identical), tropical clawed frog prrg4 (33% identical). Paralogues in human: PRRG1 (22% identical), PRRG3 (20% identical), OVCH2 (16% identical).
Diseases named in the same sentence as PRRG4 in open-access papers:
PRRG4 is named in the same sentence as 22 diseases in open-access papers, as found by Europe PMC text mining. Sharing a sentence is not in itself a finding about the gene and the disease. The quoted sentences say what the papers report.
WAGR syndrome (9 papers, 2013 to 2025). WAGR syndrome (Wilms tumor - aniridia - genitourinary anomalies - intellectual disability mental retardation) is a rare genetic disorder characterized by an unusual complex of congenital developmental abnormalities with intellectual disability, and an increased risk of developing Wilms tumor. "PRRG4 has been implicated in the Wilms tumor, Aniridia, Genitourinary anomalies, and mental Retardation (WAGR) syndrome due to genetic linkage studies." (PMID 38102641, 2023). "Human patients with WAGR syndrome often display autistic features and these have been attributed to loss of one copy of PRRG4." (PMID 28859078, 2017). "Therefore, PRRG4 deletion is very likely to be the cause of autistic symptoms in patients with WAGR syndrome." (PMID 40380139, 2025). "Interestingly, haploinsufficiencies of PRRG4 or Pax 6 are candidate genes underlying ASD in patients with WAGR syndrome." (PMID 28859080, 2017). "Moreover, genetic alterations such as the deficiency in proline-rich carboxyglutamic acid protein 4 (PRRG4) have been associated with autistic features present in WAGR syndrome (Wilm’s tumour, aniridia, genitourinary anomalies and “mental retardation”)." (PMID 28859080, 2017). "The PRRG4 gene has been implicated in the autistic features of WAGR syndrome." (PMID 28859078, 2017). "Our findings support the association between PRRG4 loss and ASD phenotypes observed in WAGR syndrome." (PMID 40380139, 2025). "A study of WAGR syndrome revealed that PRRG4 is one of only three genes deleted in all of the patients tested." (PMID 23873930, 2013). "Another literature has found that severe developmental disabilities and autistic behaviors of WAGR syndrome are only shown when PAX6 or PRRG4 at 11p13 is deleted, by comparing the different phenotypes of individuals with different fragment deletions in 11p14-p12 (2 cases)." (PMID 40380139, 2025). "PRRG4 is located in the 11p13 region, relevant to WAGR syndrome." (PMID 35436926, 2022). "PRRG4 is proposed to contribute to the autistic symptoms of WAGR syndrome, but the molecular function of PRRG4 genes remains unknown." (PMID 28859078, 2017). "As autism appears to primarily be a synaptic disorder, haploinsufficiency for PRRG4 may disrupt synapse formation in WAGR syndrome." (PMID 28859078, 2017). "Similarly, studies of comm in Drosophila and other species can guide expectations of PRRG4 function in WAGR syndrome." (PMID 28859078, 2017). "Therefore, this study suggested that haploinsufficiencies of PAX6 or PRRG4 included in this region were candidate genes for severe developmental delay and autistic features characteristic of WAGR syndrome." (PMID 26605098, 2015). "In addition, the result of our study also suggests that PRRG4, a potential candidate gene for WAGR syndrome, may regulate long range axon extension by modulating mitochondrial function during embryonic development." (PMID 38102641, 2023).
autism (6 papers, 2013 to 2025). Persistent deficits in social interaction and communication and interaction as well as a markedly restricted repertoire of activity and interest as well as repetitive patterns of behavior. "In a survey of 31 WAGR patients with autism, all were deleted for PRRG4, a correlation that suggested that PRRG4 is involved in autistic symptoms." (PMID 28859078, 2017). "PRRG4 expression has been observed in Purkinje cells in the human cerebellum, neurons known to be important in autism models." (PMID 28859078, 2017). "It has been reported that the proline-rich and Gla domain 4 (PRRG4) gene may play a role in the development of autism and neurodevelopment." (PMID 40380139, 2025). "It has been suggested that deletion of PRRG4 (proline-rich and Gla domain 4) deletion may contribute to autism symptoms in patients with WAGR (Wilms’ tumor, aniridia, gonadoblastoma, mental retardation) syndrome." (PMID 40380139, 2025). "Whether PRRG4 has any role in mental retardation and autism might be identified by investigating further the function of PRRG4 protein in the nervous system." (PMID 23873930, 2013). "Candidate genes such as BDNF, ELP4, PRRG4, and SLC1A2 have been identified in relation to autism, cognitive/developmental delays, and behavioral problems." (PMID 34970513, 2021).
breast carcinoma (5 papers, 2022 to 2025). "PRRG4 knockdown leads to a prominent decrease in the mtDNA content in breast cancer cells, which likely contributes to the decrease in mRNA levels of the 13 mtDNA protein-encoding genes and impaired mitochondrial functions in PRRG4 knockdown cells." (PMID 38102641, 2023). "Interestingly, in addition to Ndfip proteins, the PRRG4 protein has also been implicated in the regulation of Robo1 receptors in vitro, and in the context of breast cancer tumor metastases, PRRG4 has been shown to regulate Robo1 degradation through recruitment of Nedd4." (PMID 40496139, 2025). "In this study, through a transcriptome analysis of breast cancer cells with PRRG4 knockdown by PRRG4 shRNAs, we uncovered a link between PRRG4 and cell motility through mitochondria in breast cancer cells." (PMID 38102641, 2023). "PRRG4 was found to boost metastasis in an experimental metastasis model and to promote the migration and invasion of breast cancer cells in experiments including PRRG4 overexpression and knockdown." (PMID 38137332, 2023). "We have shown recently that PRRG4 promotes the migration, invasion, and metastasis of breast cancer cells by binding the E3 ubiquitin ligase NEDD4 via its PY motifs, degradating Robo1, and activating FAK and Src." (PMID 38102641, 2023). "Luciferase activities in breast cancer cells transiently transfected with these reporter plasmids were analyzed to examine the effects of PRRG4 overexpression on promoter activity." (PMID 38102641, 2023). "Our published result showed that PRRG4 promotes the migration and metastasis of breast cancer cells." (PMID 38102641, 2023). "Our results demonstrate that STAT3 inhibition significantly reduced PRRG4-induced increase in oxygen consumption and migratory behaviors of breast cancer cells." (PMID 38102641, 2023). "Our results reveal that PRRG4 promotes migration and invasion of breast cancer cells by modulating mitochondrial function through the Src-STAT3-POLG axis." (PMID 38102641, 2023). "To investigate this possibility, we examined the effect of PRRG4 knockdown on STAT3 activation in breast cancer cells by immunoblotting with phospho-STAT3 (Tyr705) antibody (p-STAT3)." (PMID 38102641, 2023). "Our previous study has shown that PRRG4 interacts with endogenous Src and enhances Src activation, which likely mediates PRRG4-induced migration and invasion of breast cancer cells." (PMID 38102641, 2023). "Further research is certainly required to specifically link PRRG4-induced oxidative phosphorylation and migratory behaviors of breast cancer cells." (PMID 38102641, 2023). "Taken together, our results indicate that STAT3 mediates PRRG4-induced POLG expression in breast cancer cells." (PMID 38102641, 2023). "To explore the molecular mechanism of PRRG4 action in breast cancer, we performed RNA-seq of SKBR3 cells expressing control-shRNA and two different PRRG4-shRNAs." (PMID 38102641, 2023). "Our recent study revealed that transmembrane protein PRRG4 promotes the metastasis of breast cancer." (PMID 38102641, 2023). "Our study uncovers that PRRG4 via Src-STAT3 regulates POLG expression by increasing the transcription of POLG in breast cancer cells." (PMID 38102641, 2023). "Transwell assays were performed to determine the effects of PRRG4-regulated pathway on migratory behaviors of breast cancer cells." (PMID 38102641, 2023). "A recent study suggested that PRRG4 plays an important role in the metastasis and invasion of breast cancer cells." (PMID 36338672, 2022). "Furthermore, results from transwell assay also revealed that POLG overexpression enhanced cell migration and invasion, and rescued the reduced cell migration and invasion induced by PRRG4 knockdown in breast cancer cells." (PMID 38102641, 2023). "In addition, while PRRG4-WT expression increased the basal and oligomycin-sensitive ATP contents compared with vector control, addition of Stattic blocked PRRG4-WT-enhanced ATP levels in both breast cancer cell lines." (PMID 38102641, 2023).
breast carcinoma (continued). "Since the transcripts of most of mtDNA-encoded genes were reduced by PRRG4 knockdown, we suspected that PRRG4 may regulate mtDNA content in breast cancer cells." (PMID 38102641, 2023). "Moreover, PRRG4 elevated migratory behaviors and mitochondrial function of breast cancer cells through POLG." (PMID 38102641, 2023). "Compared with vector only, PRRG4-WT enhanced p-STAT3 levels in breast cancer cells." (PMID 38102641, 2023). "Next, we investigated whether STAT3 mediates PRRG4-enhanced migratory behaviors of breast cancer cells by performing transwell migration and invasion assays." (PMID 38102641, 2023). "As mitochondrial DNA polymerase gamma (POLG) is essential for mtDNA replication, we hypothesized that PRRG4 may regulate mtDNA content by controlling POLG expression through STAT3 in breast cancer cells." (PMID 38102641, 2023). "Subsequently, we wanted to examine whether POLG is involved in PRRG4’s action in enhancing breast cancer cell migration and invasion." (PMID 38102641, 2023). "However, it was found that via downregulating Robo1, PRRG4 promoted breast cancer metastasis; thus, PRRG4 expression was found to be higher in breast tumors than in normal breast tissues." (PMID 38137332, 2023). "However, it is still less clear how activation of FAK-Src signaling by PRRG4 contributes to breast cancer metastasis." (PMID 38102641, 2023). "Mechanistically, PRRG4 via Src activated STAT3 in breast cancer cells." (PMID 38102641, 2023). "RNA-seq analyses were performed on breast cancer cells expressing control and PRRG4 shRNAs." (PMID 38102641, 2023). "To begin to test this possibility, we investigated whether PRRG4 regulates the formation of filopodia, which plays a key role in driving cell migration in breast cancer cells." (PMID 38102641, 2023). "Our results indicate that PRRG4 via the Src-STAT3-POLG axis enhances mitochondrial function and promotes migratory behaviors of breast cancer cells." (PMID 38102641, 2023). "In this study, we uncover that PRRG4 via the Src-STAT3-POLG axis enhances mitochondrial DNA copy number and ATP production, and promotes the migration and invasion of breast cancer cells." (PMID 38102641, 2023). "All these data indicate that PRRG4 via the STAT3-POLG pathway enhances the migration, invasion, and mitochondrial function of breast cancer cells." (PMID 38102641, 2023). "Together, these findings demonstrate that PRRG4 increases mtDNA content and promotes mitochondrial function through activation of STAT3 in breast cancer cells." (PMID 38102641, 2023). "Quantitative-PCR (qPCR) was used to verify this observation in two different breast cancer cell lines SKBR3 and SUM149PT with PRRG4 knockdown." (PMID 38102641, 2023). "Considering the reported roles of STAT3 in mitochondrial function and oxidative phosphorylation, we wanted to test whether PRRG4 can activate STAT3 via Src especially considering that Src and STAT3 are commonly involved in breast cancer." (PMID 38102641, 2023). "To detect whether STAT3 mediates PRRG4-enhanced mtDNA and ATP contents in breast cancer cells, we examined the effects of Stattic (a STAT3 inhibitor) treatment on MDA-MB-231 or HCC1954 cells overexpressing PRRG4-WT." (PMID 38102641, 2023). "Therefore, PRRG4 via STAT3 likely promotes mitochondrial biogenesis and oxidative phosphorylation to enhance the migration of breast cancer cells." (PMID 38102641, 2023). "In addition, PRRG4-mediated activation of STAT3 also enhanced filopodia formation, migration, and invasion of breast cancer cells." (PMID 38102641, 2023). "However, it is not clear whether PRRG4 can affect the migration and invasion of breast cancer cells through regulating mitochondria function." (PMID 38102641, 2023).
endometriosis (3 papers, 2022 to 2025). The growth of functional endometrial tissue in anatomic sites outside the uterine body. "To further explore the underlying mechanism of miR-519b-3p in endometriosis, we used TargetScan to predict whether Prrg4 might be the target gene of miR-519b-3p." (PMID 36338672, 2022). "LncRNA HOTAIR is involved in the development of endometriosis by promoting endometrial stromal cell invasion and migration by increasing PRRG4 expression through sponging of miR-519b-3p." (PMID 40457415, 2025). "To clarify the relationship among LncRNA HOTAIR, miR-519b-3p, and PRRG4 in endometriosis, we conducted a rescue experiment." (PMID 36338672, 2022). "The qRT-PCR analysis results showed that the expression level of PRRG4 increased in endometriosis, especially in ectopic endometrial tissues." (PMID 36338672, 2022). "The present study aimed to investigate whether LncRNA HOTAIR regulates cell invasion and migration in endometriosis by regulating the miR-519b-3p/PRRG4 pathway." (PMID 36338672, 2022). "The LncRNA HOTAIR/miR-519b-3p/PRRG4 pathway was involved in the pathogenesis of endometriosis and might be a potential marker and new target for early diagnosis and treatment of endometriosis." (PMID 36338672, 2022). "Thus, miR-519b-3p may mediate the elevation of PRRG4 in endometriosis." (PMID 36338672, 2022).
Anxiety (1 paper, 2025). Intense feelings of nervousness, tension, or panic often arise in response to interpersonal stresses. "However, the social novelty deficits and the anxiety symptoms of male PRRG4-CKO mice were more pronounced than in female PRRG4-CKO mice." (PMID 40380139, 2025). "The results of both tests showed that male PRRG4-CKO mice had anxiety symptoms, and the ASD-like behaviors of male PRRG4-CKO mice were more pronounced than in female PRRG4-CKO mice." (PMID 40380139, 2025). "The PRRG4 brain-specific knockout (PRRG4fl/fl-Cre+, PRRG4-CKO) mice exhibited social deficits, repetitive behaviors, and anxiety-like symptoms compared to PRRG4fl/fl control mice according to the results of various behavioral tests." (PMID 40380139, 2025).
ovarian endometriosis (1 paper, 2022). A non-neoplastic disorder characterized by the growth of endometrial tissue in the ovaries. "To investigate the expression level of PRRG4, we evaluated the ectopic and eutopic endometrial tissues from 20 patients with ovarian endometriosis and 10 control patients with normal endometrial tissues by qRT-PCR." (PMID 36338672, 2022).
tumor (6 papers, 2013 to 2025). "In this study, we predicted candidate genes targets of miR-1229, among which PRRG4, REEP5, and PSMB5 were associated with a poor prognosis and highly expressed in tumor tissues." (PMID 33854621, 2021).
cancer (4 papers, 2019 to 2023). A tumor composed of atypical neoplastic, often pleomorphic cells that invade other tissues. "In summary, our study uncovers that PRRG4 promotes the invasion and metastasis of cancer cells by modulating mitochondrial function through the Src-STAT3-POLG axis." (PMID 38102641, 2023). "Recent studies have begun to reveal the important roles of PRRG4 in cancer progression." (PMID 38102641, 2023).
neurological disorders (1 paper, 2013). "Further analysis of the PRRG4-interacting proteins identified in this study may help to elucidate the role of PRRG4 in cancer, allergy, and neurological disorders." (PMID 23873930, 2013).
PRRG4 also shares sentences with these, for which no sentence is quoted: developmental delay (3 papers); Wilms tumor (3); aniridia (2); autism spectrum disorder (1); breast tumors (1); cholangiocarcinoma (1); colorectal cancer (1); Epileptic encephalopathy (1); gonadoblastoma (1); Kleefstra syndrome (1); mental retardation (1); neurodegenerative disease (1); papillary thyroid carcinoma (1).